HMGB1 (high mobility group box 1)
Diseases named in the same sentence as HMGB1 in open-access papers (continued):
Sharing a sentence is not in itself a finding about the gene and the disease.
infection (continued). "Furthermore, we found that the high mobility group box 1 protein (HMGB1), a marker of necrosis as cell membranes rapture, was markedly increased in the supernatant of MV-Edm-infected cells 48 and 72 h post-infection." (PMID 25004098, 2014). "HMGB1 bands were detected as early as 6 hours post infection." (PMID 24342460, 2013). "HMGB1 has been suggested as a ligand for TLR2 in signaling following infection with different poxviruses as it is released during cell death and many attenuated strains of vaccinia virus cause widespread cell death, having lost molecules which inhibit apoptosis in the parent strain." (PMID 23844129, 2013). "The development of absorption columns for circulating nuclear antigens (histone H1 and HMGB1) as well as neutralizing humanized monoclonal antibodies may help to establish novel immunotherapies for infection, injury, inflammation, and transplant rejection." (PMID 23690821, 2013). "Similar observations were found in rats after one day and three days of infection (data not shown), indicating that the NF-κB pathway is not implicated in the previously observed release of HMGB1 and following cell death in this model." (PMID 23301002, 2013). "High-mobility group box 1 (HMGB1) is a DAMP that may be of particular interest as it is associated with delayed and sustained release during infection." (PMID 24342460, 2013). "A positive feedback mechanism may enhance the release of HMGB1 as the infection progresses, enabling the protein to reach a level to mediate the symptoms of DHS/DSS." (PMID 22860034, 2012). "Besides its canonical DNA transactions within the nucleus, HMGB1 was recently recognized as an inflammatory mediator actively secreted as a cytokine by macrophages and other inflammatory cells upon cell injury and infection." (PMID 22723938, 2012). "Furthermore, HMGB1 dominantly reside in the nucleus and DV capsid protein enters the nucleus during infection." (PMID 22860034, 2012). "After burn injury, HMGB1 is released passively during cell injury, and is actively secreted by macrophages and other cell types activated by exposure to products of thermal injury or infection." (PMID 23209806, 2012). "Taken together that HMGB1 predominantly reside in the nucleus and DV capsid protein enters the nucleus during DV-infection, we hypothesize DV capsid protein may play a role in mediating the release of HMGB1." (PMID 22860034, 2012). "Besides regulating transcriptional processes, HMGB1 also acts as a pro-inflammatory cytokine once released into the extracellular environment during tissue injury and infection." (PMID 22860034, 2012). "Initial experiments were performed to determine whether DV-infection induces the translocation of HMGB1 from the nucleus to the cytoplasm in K562 cells." (PMID 22860034, 2012). "The data presented here show that BAT3 may behave similarly to a nuclear immune regulatory factor, such as HMGB1, that is released by DCs and macrophages in response to endotoxin shock and infection, as reviewed elsewhere." (PMID 22808273, 2012). "HMGB1 released by HSV-2 infected cells might contribute to signaling of the infection and modify the environment of infected cells in vivo." (PMID 21283827, 2011). "Finally, we show that genital HSV-2 active infections also promote HMGB1 release in vivo, strengthening the clinical relevance of our experimental data." (PMID 21283827, 2011). "However, we show here that late release of HMGB1 by infected epithelial cells displays at least two biological activities that are highly relevant to herpetic infection." (PMID 21283827, 2011). "Furthermore, the increased concentration of HMGB1 in the cell culture supernatant observed after H37Rv infection was dependent on an intact ESAT-6 gene." (PMID 21637850, 2011). "Under stress conditions such as injury and infection, HMGB1 is released and promotes inflammation." (PMID 20497537, 2010).
infection (continued). "The nuclear DNA-binding protein high mobility group box 1 (HMGB1) can be passively released by necrotic cells or secreted by macrophages and other myeloid cells in response to inflammatory stimuli as part of the inflammatory response to infection or injury." (PMID 20799933, 2010). "IL-1α and HMGB1 were thus defined as endogenous ‘danger’ signals or ‘alarmins’ that may alert the immune system after cell and tissue damage during trauma or infection." (PMID 18836528, 2008). "Based on these findings, we speculate that IL-33 may function, similarly to the prototype ‘alarmin’ HMGB1, as an endogenous ‘danger’ signal to alert the immune system after endothelial or epithelial cell damage during trauma or infection." (PMID 18836528, 2008). "• HMGB1 is a proinflammatory cytokine in severe infections and bacteraemia." (PMID 17625012, 2007). "Therefore, we hypothesize that increased levels of HMGB1 may predict the development of intestinal inflammation in the experiment, which would last longer than 24 h post‐infection." (PMID 41474380, 2026). "Likewise, HBV+DEN-treated liver showed elevated high-mobility group box 1 (HMGB1) expression, a well-known damage-associated molecular pattern (DAMP) molecule and TLR4 agonist, in hepatocytes compared with Sham+DEN-treated liver at 4 months post-infection." (PMID 40579434, 2025). "MA10 infection induced six down-regulated (Pllp, Malat1, Myrf, Mag, Ptgds, Ugt8a) and two upregulated DEGs (Sgk1, Mbp), while Aβ pathology resulted in one down-regulated (Hmgb1) and ten up-regulated DEGs (Apoe, B2m, Clu, Cstd, Gfap, Psen1, Pllp, Cst7, Cd9, Plp1)." (PMID 41497643, 2025). "Thus, we investigated the localization of HMGB1 in RCs during HAdV-C5 infection of HFFs." (PMID 39611842, 2025). "We investigated whether infection could lead to different redox forms of HMGB1." (PMID 40872763, 2025). "Additionally, endogenous molecules such as immunoglobulins, antithrombin, thrombomodulin, vasoactive intestinal peptide, and growth hormone-releasing peptide have demonstrated potential in reducing HMGB1-mediated inflammation in various conditions, including infections and chemical toxicity." (PMID 40688353, 2025). "Thus, in the presence of cellular stressors, such as stretch, OS, and infection, hAECs have been shown to induce a proinflammatory stress response marked by NF-κB activation, secretion of proinflammatory cytokines, and secretion of HMGB1 and cffDNA in vitro." (PMID 38791199, 2024). "Additionally, this study highlighted the role of extracellular HMGB1 in inflammation and infection." (PMID 37667233, 2023). "Several possible reasons exist for these seemingly contradictory outcomes: the disruption of the plasma membrane by Ninjurin 1 during lytic cell death, including pyroptosis, might also contribute to HMGB1 release and F3 activation during lethal infection in mice." (PMID 38020710, 2023). "In addition to LPS, accumulating evidence has documented that exogenous microbial products, various pathogen infections, and endogenous host stimuli can induce active HMGB1 secretion in multiple cells, such as, but not limited to, immune cells, fibroblasts, and epithelial or endothelial cells." (PMID 35217834, 2022). "Interestingly, HMGB1 was detected in cell supernatants at 72 hpi, suggesting that infection induced a passive release of HMGB1 by necrotic cells, which could be a factor that enhances the inflammation observed during DENV disease." (PMID 36016387, 2022). "Subsequently, it has been reported that HMGB1 could be actively secreted by natural killer cells, monocytes, platelets, endothelial cells, and dendritic cells, and passively released from the nuclei of damaged/necrotic cells during infection." (PMID 36189354, 2022). "Therefore, the decrease in disease of the TLR4mut mice during VEEV TC-83 infection might in part be mediated by a decrease in HMGB1 driven pro-inflammatory effects, although this remains to be experimentally demonstrated." (PMID 33487119, 2021).
infection (continued). "HMGB1, passively secreted by necrotic hepatocytes, may stimulate tissue macrophages especially Kupffer cells to express proinflammatory cytokines during an acute infection." (PMID 33505216, 2021). "Therefore, it is possible that accumulated extracellular HMGB1 not only exacerbates secondary damaging process by aggravating inflammation in the postischemic brain but also make animals vulnerable to the following infection." (PMID 29555931, 2018). "Interestingly, plasma levels of HMGB1 were related to the occurrence of postoperative infections." (PMID 29675023, 2018). "Thus, HMGB1 levels at the site of infection may best reflect the severity of disease in bacterial infections." (PMID 30194360, 2018). "In the context of epithelial cells, LPS transfection of IEC led to HMGB1 release and infection of gingival epithelial cells with Fusobacterium nucleatum drove release of HMGB1 alongside Asc and IL-1β secretion, suggesting that inflammasomes may be involved in the active secretion of HMGB1 from IEC." (PMID 28979266, 2017). "Accumulating evidence indicates that HMGB1 functions as an alarmin, forming immune stimulatory complexes with chemotactic factors that promote the migration of leukocytes, activation of lymphoid cells, and augment the inflammatory response, which correlate with severity of infection." (PMID 27667993, 2016). "Therefore, we performed antibody neutralization experiment to investigate whether the infection could be inhibited after the HMGB1 protein was neutralized." (PMID 27634894, 2016). "During early infection there is a highly oxidizing environment produced by numerous activated macrophages that actively produce ROS and NO, and apoptotic macrophages that liberate oxidized HMGB1, that temporally suppress excessive inflammation and decrease protective immunity." (PMID 26201072, 2015). "TSN-SS has already been used in China as a medicine for patients with cardiovascular disorders, and its capacity to facilitate endocytic HMGB1 uptake by professional phagocytes may provide basis for the treatment of both infection- and injury-elicited inflammatory diseases." (PMID 25821489, 2015). "Thus, our data indicate that FIP200 may regulate HMGB1 translocation to cytosol following PAO1 infection via direct molecular interaction with HMGB1." (PMID 24923305, 2014). "Thus, intranuclear and extranuclear HMGB1 are therapeutic targets for inflammation and infection." (PMID 24944700, 2014). "Therefore, DV capsid protein may play a role in mediating HMGB1 release during wild-type DV-infection involving the acetylation pathway." (PMID 22860034, 2012). "An alternative and more likely possibility is that IL-33 may be released from dead or dying cells during trauma or infection, and may function, similarly to HMGB1, as an endogenous ‘danger’ signal or ‘alarmin’, to alert the immune system of cell or tissue damage." (PMID 18836528, 2008). "In summary, our data show that infection of DF-l cells by IBDV induced chGSDME cleavage, LDH and HMGB1 release, and cell death." (PMID 39576037, 2025). "HMGB1, an early proinflammatory protein, can be actively secreted under stimulation by Lipopolysaccharide (LPS), TNF-α, infection and endogenous host stimuli or passively released under conditions of cell apoptosis and necrocytosis." (PMID 39883639, 2025). "Confocal microscopy was also consistent with co-localization of HMGB1 and CRM1 in the nucleus upon HAdV-D37 infection, as compared to mock controls." (PMID 40367285, 2025). "Because infection induced the infiltration of immune cells even in the absence of HCF in the construct, it appeared that the expressed HMGB1 was acting as a chemokine, consistent with a reduced form of the molecule." (PMID 40367285, 2025). "Infection, virus replication, and SS cell growth inhibition correlated with induction of stress and DAMP marker expression, including calreticulin and HMGB-1." (PMID 41235176, 2025).
infection (continued). "Within the infection group, PTA patients showed significantly higher CRP (p = 0.036) and HMGB1 (p = 0.003) levels and lower kallistatin (p < 0.001) levels compared to PTC patients." (PMID 41153226, 2025). "After drainage, HMGB1, IL-1, IL-6, and TNF-α in the bile of AOSC patients were reduced as infection decreased." (PMID 40054422, 2025). "Immunofluorescence staining of E. coli-infected endometrial explants showed that PGD2 treatment led to an increased expression of HMGB-1 and HABP-2 at 9 h post-infection (P < 0.0001)." (PMID 40874199, 2025). "In conclusion, we showed that in a mouse model of Pm infection, GA significantly reduced Pm-induced vascular inflammatory injury, and decreased PARP1, HMGB1, IL-1β, and IL-18 protein expression in vascular tissue." (PMID 39850582, 2024). "In fact, intestinal epithelium expressed HMGB1 downregulates STAT3 activation and augments autophagic cascades for protection from infection." (PMID 39682695, 2024). "HMGB1 is discharged into the extracellular area in numerous forms of RCD and is correlated to the genesis of inflammation, both due to infections and aseptic." (PMID 36675299, 2023). "During infection, protein VII interacts with and sequesters in chromatin the host alarmin high mobility group box 1 (HMGB1)." (PMID 37703278, 2023). "Further exploration of the collaboration between HMGB1 and NFE2L2-targeted genes in infection and innate immunity is important." (PMID 35217834, 2022). "In these mice, GLY was able to protect the cornea by lowering clinical scores at both 3 and 5 days after infection and downregulating TLR9, HMGB1 and RAGE after infection." (PMID 36422579, 2022). "HMGB1 in WT group and WTSJ group was 1164.00 ± 201.00 and 27,820.00 ± 8612.00 pg/ml, respectively, indicating a 23.9-fold increase after infection." (PMID 35505421, 2022). "Hence, as an alarmin, HMGB1 may be expelled in response to “danger” (infection, injury, stress) in order to sample the external environment, with this HMGB1-bound material then ingested to initiate intracellular recognition and guide the cellular response (and host defence)." (PMID 35712662, 2022). "Comparing B6 and TLR4KO, GLY treatment reduced clinical scores and improved disease outcome after infection and decreased mRNA expression levels in cornea for TLR4, HMGB1, and RAGE in B6 mice." (PMID 36422579, 2022). "The levels of IL-6, IL-8, HMGB-1, and IFN-β RNA transcripts increased in a time-dependent manner after infection." (PMID 33796483, 2021). "For example, NO level is associated with vasoconstriction, pro-inflammatory and cell-mediated immunity (CMI) cytokines, HMGB1, IL-33, neopterin, ICAM1, and complement components are most related to inflammation and infection." (PMID 34679434, 2021). "In this regard, there is also evidence for the participation of another nuclear protein, High-Mobility Group Box-1 (HMGB1), as part of the cytokine storm triggered during the inflammatory response to infection." (PMID 34576097, 2021). "HMGB1 can favor HIV replication, but regulatory microRNAs can outweigh its production to avoid local infection." (PMID 32983090, 2020). "The ISD bait method was validated by identifying known dsDNA sensors including HMGB1, HMGB2, and HMGB3, components of the AIM2 inflammasome, and the SET complex that plays a role in HIV-1 retroviral detection and infection." (PMID 33042865, 2020). "It is worth noting that 3 studies have published links between type 2 inflammation and HMGB1 in animals infected with pneumonia virus of mice (PVM), a murine virus that results in infection similar to that of severe RSV-induced infection in infants." (PMID 32397226, 2020). "Anti-HMGB1 therapy significantly reduced the concentrations of IL-4, IL-5, and IL-13 in the BALF at day 21 post-infection compared to a group that was infected and treated with control antibodies." (PMID 32397226, 2020).
infection (continued). "Extracellular ATP levels were raised 24 h after infection (OAd.TNFa-IL2 vs. mock p = 0.002) and extracellular HMGB1 levels were raised after 48 h (OAd.TNFa-IL2 vs. mock p = 0.0114)." (PMID 32225009, 2020). "IB analysis of the concentrated supernatants from NDV‐infected DU145 and PC‐3 cells revealed an evident increase in the protein levels of HMGB1 and HSP70/90 at 48 hours following NDV/FMW infection compared with mock‐infected cells.." (PMID 32100392, 2020). "High mobility group box 1 (HMGB1) is a prototypical DAMP and a central mediator of lethal inflammation in infection and tissue damage." (PMID 33313438, 2020). "Among them, HMGB1 is a key DAMP, which plays a pathological role in various infections and sterile inflammation by activating innate and adaptive immunity." (PMID 33313438, 2020). "In both PNET models, the infection with VCN-01 mediates a significant increase in secreted Hsp90, HMGB1 and ATP, ranging from 1.6 to 5.2 times higher than in mock infected cultures." (PMID 31591461, 2019). "HMGB1 has also been recognized as a DAMP that elicits a TLR4-dependent cytokine storm when released from necrotic cells in response to injury, infection, or other inflammatory stimuli." (PMID 29535197, 2018). "Overall, the release of HMGB1 protein into serum upon infection with RSV and HRVs mimic their strength of infection and reported inflammatory and pathology profile in cotton rats (30, –, 32)." (PMID 29535197, 2018). "In vivo, after G81007 infection, GLY treatment reduced clinical score and messenger RNA (mRNA) expression of IL-1β, TNF-α, CXCL2 and HMGB1." (PMID 29064403, 2017). "Mode of cytotoxicity displayed features consistent with oncosis, and infection with EnAd led to release of the pro-inflammatory markers heat shock protein 70 (HSP70) and high-mobility group box-1 (HMGB1) from cells." (PMID 28791251, 2017). "The Salmonella counts, Activated Neutrophil, NET, TNF-α, HMGB-1, MDMI, and MDMII levels in the simulation sharply increased at the beginning of the infection but progressively decreased as the infection progressed." (PMID 27556404, 2016). "Understanding the interactions other than those of HMGB1 and RAGE is required to further investigation the molecular patterns involved in immune sensing following infection with H. pylori." (PMID 27667993, 2016). "The combination of anti-HMGB-1 and anti-TNF-α was more effective in improving the survival rates when treatment was started between 7 hours and 11 hours after infection, compared to using only anti-TNF-α." (PMID 27556404, 2016). "We examined the impacts of SIRT1 activator resveratrol (RES) and its inhibitor nicotinamide (NIC) on HMGB1 release and PEDV infection." (PMID 27634894, 2016). "H. pylori-induced HMGB1 and RAGE expression peaked with 6 h of infection and decreased after incubation for 16–24 h." (PMID 27667993, 2016). "Subsequently, levels of HMGB1, a ubiquitously expressed, cytokine-like protein that can activate TLR4 and potentiate cytokine responses, increase about 16 hours after infection and remain elevated for several days." (PMID 26695754, 2015). "We also observed that FIP200 siRNA silencing in MH-S cells significantly decreased protein expression of HMGB1, RAGE and TLR4 following infection by western blotting." (PMID 24923305, 2014). "Cytokines and alarmins like high-mobility group box 1 (HMGB-1) directly impair endothelial function disrupting tight junctions and contributing to the blood-brain barrier (BBB) opening during infection and trauma." (PMID 25170959, 2014). "The activation of NK cells of adult mice is increased after RRV infection, and these activated NK cells eliminate RRV-infected cholangiocytes shortly after infection, decrease the persistent RRV infection and continuous HMGB1 release." (PMID 24651485, 2014). "HMGB1 release from nuclei began 12 hours after RRV incubation, and a large amount of nuclear HMGB1 in the nuclei was released extracellularly at 24 and 36 hours after RRV infection." (PMID 24651485, 2014).